AIM2 (absent in melanoma 2)
Diseases named in the same sentence as AIM2 in open-access papers (continued):
Sharing a sentence is not in itself a finding about the gene and the disease.
atherosclerosis (50 papers, 2015 to 2025). A disease characterized by the build-up of fatty material and calcium deposition in the arterial wall resulting in partial or complete occlusion of the arterial lumen. "As a known member of the inflammasome family, the AIM2 inflammasome has been implicated in promoting ischemic cardiomyopathy, the progression of atherosclerosis, aortic aneurysms, and ischemic strokes." (PMID 38247800, 2024). "Increased cholesterol biosynthesis and ER cholesterol content have been associated with cholesterol-induced AIM2 inflammasome activation and the AIM2 inflammasome promotes atherosclerosis in Jak2V617F CH." (PMID 38522750, 2024). "First, it is important to underline that in mice with advanced atherosclerosis, activation of the dsDNA sensing AIM2 inflammasome induced a marked release of the proatherogenic cytokines IL-1β and IL-18." (PMID 36672621, 2023). "Important functional molecules that result in pyroptosis, including NLRP3, AIM2, and caspase-1, are abundantly expressed and activated in atherosclerosis and are associated with the occurrence, accumulation, and destabilization of atherosclerotic plaques." (PMID 35096837, 2021). "Overall, our data suggest that AIM2 is an active participant in atherosclerosis and underline the importance of further studies focused on the effects of AIM2 activation and inhibition for possible therapeutic targeting." (PMID 33263007, 2020). "Moreover, a recent study on the implication of AIM2 inflammasome to atherosclerosis reveals new mechanism for clonal hematopoiesis-associated atherosclerosis." (PMID 35641492, 2022). "In a murine model of CHIP (JAK2V617F mutation, commonly found in elderly individuals with CHIP), AIM2 activation in myeloid cells was shown to drive excessive IL-1β release, macrophage proliferation, and plaque destabilization, all of which accelerate atherosclerosis." (PMID 40725015, 2025). "In atherosclerosis, AIM2 and its ligand dsDNA are increased in macrophages at advanced disease stages in HFD fed ApoE‐deficient mice." (PMID 39158380, 2025). "Overall, AIM2 signaling drives the pathogenesis of cardiovascular diseases such as atherosclerosis, AAA, and heart failure." (PMID 39158380, 2025). "Deletion of AIM2 or Gsdmd reduces atherosclerosis, suggesting a role of AIM2-mediated pyroptosis in AS." (PMID 40433411, 2025). "AIM2 signaling contributes to the development of various cardiovascular diseases, such as atherosclerosis, abdominal aortic aneurysm (AAA), and heart failure." (PMID 39158380, 2025). "Recent findings highlight AIM2 as a mechanistic link between age-associated CHIP and atherosclerosis progression." (PMID 40725015, 2025). "AIM2 inflammasome‐dependent cytokines IL‐1β128 and IL‐18129 contribute to atherosclerosis plaque progression and instability." (PMID 39158380, 2025). "It has been shown that AIM2 expression levels increased with elevated oxidative DNA damage and DNA replication stress in atherosclerosis-prone JAK2VF mice." (PMID 40433411, 2025). "Emerging evidence reveals that activation of the AIM2 inflammasome is involved in the development of cardiovascular diseases, such as atherosclerosis, myocardial infarction, aortic aneurysm, and heart failure." (PMID 38247800, 2024). "During this process, the AIM2 inflammasome in macrophages not only contributed to the induction of vascular cell adhesion protein-1 (VCAM-1) expression in atherosclerosis, but also limited cholesterol transport and facilitated foam cell formation." (PMID 39600708, 2024). "In vascular smooth muscle cells (VSMCs), AIM2 had been shown to exacerbate the progression of atherosclerosis and accelerate plaque formation by facilitating endothelial cell migration and apoptosis." (PMID 39600708, 2024). "In the advanced stages of atherosclerosis, the AIM2 inflammasome within macrophages contributed to the formation of necrotic cores in atherosclerotic lesions." (PMID 39600708, 2024).
atherosclerosis (continued). "AIM2 promoted the development of atherosclerosis by enhancing endothelial cells migration and apoptosis." (PMID 39600708, 2024). "AIM2 contributed to the acceleration of atherosclerosis and enhanced plaque instability, particularly in the context of clonal hematopoiesis associated with the JAK2VF mutation." (PMID 39600708, 2024). "The recognition stimulates the activation of AIM2 inflammasome in macrophages, leading to the production of IL-1β and IL-18 in atherosclerosis." (PMID 38774746, 2024). "dsDNA-driven AIM2 inflammasome responses are emerging as critical responses in the worsening of multiple diseases including atherosclerosis, cancer, ischemic stroke, and post-stroke immunosuppression." (PMID 37216118, 2023). "Inhibition of AIM2 also reduced IL-1β and IL-18 expression levels in vascular endothelial cells in atherosclerosis-prone mouse model." (PMID 36742336, 2023). "AIM2-mediated secretion of IL-1β upregulates IL-17 release by T cells of a murine model of atherosclerosis, which then drives chemokines such as CXC motif chemokine ligand 1 (CXCL1) and CXCL2 to recruit more neutrophils during inflammation." (PMID 36742336, 2023). "While NLRP3 is a key regulator of inflammasome activation, there is increasing evidence that other inflammasome sensors, such as NLRC4 and AIM2, also play a role in atherosclerosis." (PMID 37175869, 2023). "Recent studies have confirmed that AIM2 is related to atherosclerosis, myocardial infarction, heart failure, and abdominal aortic aneurysm." (PMID 35646157, 2022). "Circular RNA PPP1CC was recently shown to stimulate Porphyromonas gingivalis LPS‐induced pyroptosis in vascular smooth muscle cells, by AIM2 activation through the HMGB1/TLR9/AIM2 pathway, also promoting atherosclerosis." (PMID 35832835, 2022). "Given the known role of NLRP3 inflammasome in atherosclerosis, it is possible that AIM2 promotes the development of atherosclerosis partially through activating the NLRP3 inflammasome." (PMID 35464402, 2022). "Former strong evidence has shown that AIM2 was involved in atherosclerosis, and a high level of AIM2 was expressed in atherosclerotic plaque of the human carotid artery and mice." (PMID 35646157, 2022). "JAK2 mutation showed increased expression of absent in melanoma 2 (AIM2), DNA replication stress, oxidative DNA damage, and multiple inflammatory pathway, thereby aggravating atherosclerosis." (PMID 34576030, 2021). "Activation of inflammasomes, such as Nlrp3 and AIM2, can exacerbate atherosclerosis in mice and humans." (PMID 34395445, 2021). "Herein, we have reported that AIM2 has an important role in the development and progression of atherosclerosis." (PMID 33263007, 2020). "The deletion of AIM2 rescues Apoe−/− mice from atherosclerosis." (PMID 39158380, 2025). "All other inflammasomes remain poorly understood in atherosclerosis, except AIM2, NLRP1, and NLRC4." (PMID 40564905, 2025). "Therefore, oxidative DNA damage and DNA replication stress caused by increased proliferation and glycolytic metabolism in Jak2VF macrophages leads to activation of the AIM2 inflammasome, aggravating atherosclerosis." (PMID 39158380, 2025). "The AIM2 inflammasome has also emerged as a pro-inflammatory entity in atherosclerosis." (PMID 40564905, 2025). "Interestingly, one study observed that larger quantities of double-stranded DNA colocalized with AIM2 in the aortic arch of mice in advanced stages of atherosclerosis." (PMID 40508226, 2025). "Like ASXL1, JAK2 VF CHIP also drives atherosclerosis by activating the AIM2 inflammasome." (PMID 39352379, 2024). "Similarly, in conditions such as coronary artery disease (CAD) and diabetes, the AIM2 inflammasome activation exacerbated atherosclerosis." (PMID 39600708, 2024). "AIM2 also detects self-derived DNA with noted roles in the immune response to tumors, radiation-induced tissue damage, and the DNA-damage response in mouse models of neurodevelopment, polyarthritis, and atherosclerosis." (PMID 38918243, 2024).
atherosclerosis (continued). "In addition to NLRP3-mediated inflammation, the AIM2 inflammasome also played a role in atherosclerosis in relation to CH." (PMID 39682303, 2024). "The AIM2 inflammasome, for example, has been demonstrated to modulate innate immune sensors and induce inflammatory signaling, therefore contributing to the inflammatory milieu of atherosclerosis." (PMID 38693141, 2024). "Although AIM2 inflammasome activation has been shown to be sufficient to promote atherosclerosis in Jak2 CH, our findings suggest that other pathways may also contribute to ASXL1-mediated CVD risk." (PMID 37498674, 2023). "Interestingly, this AIM2-dependent form of inflammation-aggravated atherosclerosis, with accelerated necrotic core formations was reversed by knockout of caspase-1/11 or GSDMD." (PMID 37863894, 2023). "Aside from the direct role in AS, AIM2 also has an indirect effect on atherosclerosis." (PMID 35464402, 2022). "(iv) AIM2 inflammasome activation and atherogenic proinflammatory factor interleukin-1β (IL-1β) and interleukin-18 (IL-18) release promote inflammatory responses of atherosclerosis." (PMID 35646157, 2022). "Absent in melanoma 2 (AIM2)-dependent macrophage pyroptosis exacerbates atherosclerosis as well." (PMID 35498045, 2022). "Absent in melanoma 2 (AIM2) is involved in atherosclerosis, and no clinical trials have explored the association between AIM2 and CAD." (PMID 35646157, 2022). "However, the blockage of circular RNA serine/threonine protein phosphatase PP1-gamma catalytic subunit (circPPP1CC) relieved the Pg-LPS-induced pyroptosis of VSMCs and atherosclerosis by inhibiting the HMGB-1/TLR9/AIM2 pathway." (PMID 35096837, 2021). "The role of AIM2 in vascular disease and atherosclerosis remains insufficiently understood." (PMID 33263007, 2020). "It seems to be worth of further exploration as a therapeutic target, and future studies focusing on the effects of AIM2 activation as well as its pharmacological inhibition may reveal promising new therapeutic concepts for the treatment of atherosclerosis." (PMID 33263007, 2020). "Mice deficient in AIM2 exhibited smaller and more stable atherosclerotic plaques despite carrying the JAK2 mutation, indicating that AIM2 contributes to the localized vascular inflammation seen in atherosclerosis while being systemically fueled by the aging-associated CHIP environment." (PMID 40725015, 2025). "AIM2 and IFI16 have also shown the other same features, such as cytosolic dsDNA sensors, ASC (apoptosis-associated speck-like protein containing a CARD)-dependent inflammasomes, regulating atherosclerosis, autoimmunity, tumorigenesis, and normal neuronal development." (PMID 38693141, 2024). "The AIM2 inflammasome is responsible for sensing cytosolic dsDNA derived from both pathogens and damaged cells, and its activation participates not only in host protection but also in some inflammatory diseases, such as psoriasis, chronic kidney injury, and atherosclerosis." (PMID 36982727, 2023). "However, this strategy might be less effective than targeting the IL-1 signal owing to the potential role of AIM2 in atherosclerosis development." (PMID 36932407, 2023). "It seems to be a promising therapeutic target that is worth exploring further, and future studies focusing on the effects of AIM2 activation as well as its pharmacological inhibition may reveal promising new therapeutic concepts for the treatment of atherosclerosis." (PMID 33263007, 2020). "Atherosclerotic lesions in Jak2VF mice show increased expression of AIM2, and deletion of AIM2 or GSDMD reverses atherosclerosis." (PMID 39158380, 2025). "However, AIM2 also recognizes dsDNA released by host cells and can contribute to the development of aseptic inflammatory diseases, such as ischemic brain damage, diabetes, atherosclerosis, and chronic nephritis, by stimulating the production and release of inflammatory cytokines." (PMID 38918243, 2024).
atherosclerosis (continued). "We used IHC to preliminarily detect the expression of GSDMD, CASP1, NLRC4, AIM2 and IL18 in advanced atherosclerosis plaques of patients." (PMID 38167983, 2024). "We identified a set of genes (GSDMD, CASP1, NLRC4, AIM2, and IL18) closely related to atherosclerosis, particularly in atherosclerotic lesions with high pyroptosis scores." (PMID 38167983, 2024). "The inflammatory corpuscle recombinant absents in melanoma 2 (AIM2) and cholesterol efflux protein ATP binding cassette transporter A1(ABCA1) have been reported to play opposing roles in atherosclerosis (AS) plaques." (PMID 38734775, 2024). "In contrast to TET2 and DNMT3A, where NLRP3 inflammasome activation appears predominant as a mechanism that drives accelerated atherosclerosis, recent data suggest that ASXL1 and JAK2 CHIP provoke activation of the AIM2 inflammasome." (PMID 39352379, 2024). "These can be explained as follows: (i) atherogenic risk factors, like LDL-C and high glucose, and cytokines involved in atherosclerosis, like tumor necrosis factor-alpha (TNF-α) and interferon-γ (IFN-γ), can upregulate AIM2 expression." (PMID 35646157, 2022). "Consistent with the knockout of AIM2, knockout of Caspase-1/11 or GSDMD alleviated atherosclerosis in mice Aim2 knockout in Jak2V617Fmice." (PMID 34122076, 2021). "Recently, absent in melanoma 2 (AIM2) inflammasome, caspase 1 and 11, and GsdmD were shown to play in role in clonal hematopoiesis mediated exacerbation of atherosclerosis." (PMID 34395445, 2021). "Though Nlrp3/AIM2 and IL-1β nexus is an emerging atherogenic pathway, the direct role of GsdmD in atherosclerosis is not yet fully clear." (PMID 34395445, 2021). "Activation of AIM2 leads eventually to activation of the inflammasome, but the role of AIM2 in vascular disease and atherosclerosis has not been well-studied." (PMID 33263007, 2020). "Higher expression of NLRP3, AIM2, and ASC could give rise to IL-1β and IL-18 secretion, promoting atherosclerosis and further destabilizing atherosclerotic plaques, which indicates their importance in cardiovascular disease pathogenesis." (PMID 30555415, 2018). "In addition, the absence of melanoma 2 (AIM2) inflammasome-mediated pyroptosis and inflammation in macrophages have been demonstrated to exacerbate atherosclerosis in clonal hemtopoiesis." (PMID 37863894, 2023). "However, despite numerous studies focusing on AIM2, its role in vascular disease and atherosclerosis is not yet fully understood." (PMID 33263007, 2020). "Finally, the authors concluded that AIM2 promotes the activity the N-terminal domain of GSDMD (GSDMD-N), which is required for pyroptosis, thereby accelerating pyroptosis in VSMC and unmasking AIM2 as an active participant in atherosclerosis." (PMID 33263007, 2020). "For example, vigorous activation of NLRP3 has been demonstrated in atherosclerosis, thus deterring NLRP3 is a feasible intervention without interfering with other inflammasome sensors AIM2, NLRP1, NLRC4, and Pyrin that are responsible for detecting bacteria and virus infection." (PMID 36932407, 2023). "However, only AIM2 was overexpressed and AIM2, but not NLRP3, deletion attenuated accelerated atherosclerosis in these mice, pointing to a more relevant role of the AIM2 inflammasome in this model." (PMID 38035089, 2023).
psoriasis (49 papers, 2013 to 2025). An autoimmune condition characterized by red, well-delineated plaques with silvery scales that are usually on the extensor surfaces and scalp. "AIM2 has been implicated in inflammatory skin diseases such as psoriasis, atopic and contact dermatitis, and viral skin infections." (PMID 40006996, 2025). "AIM2 forms a complex with various proteins upon activation, creating the AIM2 inflammasome, which is closely associated with psoriasis." (PMID 40343299, 2025). "To investigate the involvement of AIM2 in psoriasis pathophysiology, we used AIM2-deficient mice (Aim2–/–)." (PMID 39352743, 2024). "Using the IMQ-induced psoriasis model, we found that Aim2 deficiency reduces mRNA expression of the KC markers Lcn2, Krt14, and S100a9." (PMID 39352743, 2024). "To verify the correlation in vivo, we investigated the efficacy of CO in an imiquimod (IMQ)-induced psoriasis model, which has reported associations with the AIM2 inflammasome." (PMID 36982727, 2023). "Our team has proven that AIM2 is one of 15 new risk genes/loci of psoriasis through the whole-exome single nucleotide polymorphism (SNP) array for the first time." (PMID 36742336, 2023). "AIM2 polymerizes with other proteins to form the AIM2 inflammasome, which is one of the inflammasomes closely associated with psoriasis." (PMID 36742336, 2023). "The stop-gain variant in the AIM2 gene, whose definite site is rs2276405, is significantly enriched in psoriasis." (PMID 36742336, 2023). "AIM2 gene was firstly identified as a susceptibility gene for psoriasis at the genome-wide level, this gene locates at an important topological position in the gene–gene interaction network." (PMID 36118867, 2022). "Researchers investigated the correlation between the genetic pattern of AIM2 gene polymorphism and the psoriasis phenotype." (PMID 36118867, 2022). "Our group conducted a large-scale genome-wide association study in a Chinese population, and found that the rs2276405 AIM2 coding variant significantly increased the genetic risk for psoriasis in AA allele carriers." (PMID 32528469, 2020). "A stop-gained variant at psoriasis susceptibility locus AIM2 (rs2276405) which codes for a cytosolic double-stranded DNA receptor has been identified in Han Chinese population." (PMID 31130981, 2019). "Interestingly, deficiency of AIM2 reduced the development of IMQ-induced psoriasis by decreasing the production of type 3 cytokines (such as IL-17A and IL-23) and infiltrating immune cells into the inflammatory site." (PMID 39352743, 2024). "Deficiency of AIM2 reduces experimental psoriasis-like skin inflammation." (PMID 39352743, 2024). "AIM2 was identified as a susceptibility gene/locus associated with psoriasis." (PMID 39352743, 2024). "Moreover, the whole-exosome SNP array identified the AIM2 gene as a new susceptibility locus for psoriasis." (PMID 39352743, 2024). "We then took advantage of the IMQ-induced psoriasis–like model and determined whether the loss of IL-17A signaling in IL-17RA–deficient mice (IL17ra–/–) would affect AIM2 expression in the skin." (PMID 39352743, 2024). "Altogether, these results indicate that CO holds potential not only as a therapeutic material for the treatment of psoriasis and other diseases associated with the AIM2 inflammasome and cellular damage, but also as a source for further exploration of the effective active compound." (PMID 36982727, 2023). "Researchers believe that recurring immune skin diseases such as psoriasis may be associated with AIM2-mediated inflammatory memory in skin epithelial stem cells." (PMID 36742336, 2023). "Studies showed the genetic and epigenetic associations between AIM2 gene and psoriasis." (PMID 36118867, 2022). "Along this line, genetic data have also indicated an association with polymorphism in NLRP1, NLRP3, and AIM2 in psoriasis, and more recently, the association with a genetic polymorphism in inflammasome-related genes has been shown in patients with psoriatic arthritis." (PMID 34502368, 2021).